BDNF (brain derived neurotrophic factor)
Diseases named in the same sentence as BDNF in open-access papers (continued):
Sharing a sentence is not in itself a finding about the gene and the disease.
depression (continued). "The mTOR pathway is closely associated with the manifestation of depression-likebehaviors, including anxiety, depressive symptoms, and neuronal atrophy.TrkB, a functional receptor for BDNF, is activated by BDNF, inducing thePI3K/Akt/mTORC1 cascade." (PMID 40071363, 2025). "Mechanistically, escin activates hippocampal miR-223 expression, resulting in inhibition of the NF‐κB pathway but enhancement of BDNF/TrkB pathway activity, thereby reducing neuroinflammation and counteracting depression‐associated neuropathology." (PMID 41425661, 2025). "Low BDNF levels have been implicated in the pathogenesis of several neurological conditions, such as dementia, depression, schizophrenia, and anxiety disorders, where neuroinflammation is also a significant contributing factor." (PMID 40076857, 2025). "The role of BDNF signaling in the pathophysiology of depression and the mechanisms underlying antidepressant treatment are of great importance." (PMID 39920579, 2025). "Their dysregulation has been linked to altered BDNF–TrkB signaling, aberrant neurotransmitter receptor splicing, and maladaptive stress responses—all processes relevant to treatment resistance in depression." (PMID 41465113, 2025). "This study investigated the association between brain-derived neurotrophic factor (BDNF) gene polymorphisms and antidepressant response in patients with first-episode late-life depression (LLD)." (PMID 40352065, 2025). "On the other hand, the maladaptive neuroplasticity in depression is suggested to be associated with alterations in the BDNF, which suggests that physical activity can help in overcoming depression." (PMID 40149776, 2025). "Large genetic analyses confirm that BDNF variants significantly raise the risk for major depression and TLE." (PMID 40941042, 2025). "Low BDNF levels have been associated with depression, and studies have shown that antidepressant treatments can increase BDNF levels, promoting neurogenesis and improving mood." (PMID 40305200, 2025). "A prospective study in a large community showed that higher levels of BDNF are associated with a lower risk of cardiovascular events and death, independent of low-grade inflammation, body mass index, physical activity and depression." (PMID 41327464, 2025). "Evidence shows that reduced BDNF levels significantly increase the risk of depression during pregnancy and the postpartum period." (PMID 39935532, 2025). "IBS often co-occurs with depression and anxiety, psychiatric conditions associated with decreased BDNF expression in the brain." (PMID 40316902, 2025). "Previous research has demonstrated that physical activity influences brain structure and function; for example, it reduces levels of BDNF (brain-derived neurotrophic factor), which has been associated with increased anxiety and depression." (PMID 41333752, 2025). "Numerous studies have indicated that reduced BDNF levels are closely associated with the onset of depression." (PMID 39996878, 2025). "EET increases BDNF expression via multiple promoters (I, II, and III) other than IV to compensate for the pIV-BDNF deficiency in the hippocampus, and reverses depression-like behaviors of KIV mice." (PMID 40316902, 2025). "Among these, BDNF is closely associated with neuronal regeneration and repair, and its levels are significantly reduced in the brains of depression patients." (PMID 41017972, 2025). "Studies have confirmed that the BDNF concentration is reduced in mood disorders, and an increase in BDNF concentration is associated with clinical improvement in depression." (PMID 41010312, 2025). "In our study, we found a 5.6% association between the Val66Met genetic polymorphism of the BDNF gene and the risk of developing depression in Mexican mestizo patients with multiple sclerosis." (PMID 40003622, 2025). "Functionally, excess BDNF in epilepsy promotes seizure activity, while a deficiency of BDNF in depression is linked to synaptic loss and dysfunction of the stress system." (PMID 40941042, 2025).
depression (continued). "Improvements in circulating BDNF, kynurenine, and IL-6 levels were associated with reductions in depression symptoms." (PMID 40665827, 2025). "Neuroinflammation via the cyclic GMP-AMP synthase (cGAS)–stimulator of interferon genes (STING) pathway and reduced hippocampal brain-derived neurotrophic factor (BDNF) expression are key mechanisms underlying stress-induced depression." (PMID 41226472, 2025). "BDNF and Wnt signaling are interesting therapeutic targets because they converge on important neuroplasticity pathways implicated in depression." (PMID 40149774, 2025). "Emerging research suggests that alterations in brain-derived neurotrophic factor(BDNF) are associated with depression onset." (PMID 40352065, 2025). "The analysis revealed that higher levels of BDNF (OR < 1) and IL-10 (OR < 1) were significantly associated with a reduced risk of depression, suggesting a protective neurotrophic and anti-inflammatory effect." (PMID 40823578, 2025). "Decreased activation of the BDNF–TrkB signaling pathway is linked to depression in humans and mice (Castrén and Monteggia 2021)." (PMID 40590368, 2025). "The purpose of our study was to evaluate the association between the BDNF Val66Met polymorphism and depression in MS patients." (PMID 40003622, 2025). "The aim of this study was to investigate the association between the genetic type and alleles for the TPH1, TPH2, SLC6A4, HTR1A, HTR2A, and BDNF genes in Korean suicide attempters with major depressive disorder (suicide attempters) and a control group." (PMID 41300755, 2025). "Individuals with depression typically exhibit reduced brain-derived neurotrophic factor (BDNF) levels, and impaired sleep quality is also associated with alterations in BDNF concentrations." (PMID 41030341, 2025). "MD intervention, however, has been found in a randomized clinical trial to have an association with a higher plasma BDNF level in individuals with depression." (PMID 40289947, 2025). "Identifying depression in MS patients based solely on the Val66Met polymorphism in the BDNF gene presents considerable challenges." (PMID 40003622, 2025). "The dysregulation of the BDNF/TrkB system is a shared pathological hallmark across a wide range of conditions, including depression, schizophrenia, AD, PD, and HD." (PMID 40005159, 2025). "The upregulation or activation of Kir4.1 reduces BDNF expression, thereby decreasing neuronal excitability, a process associated with the pathophysiology of depression." (PMID 40001468, 2025). "Studies have shown that polymorphic variants of SERT and BDNF individually contribute to severe and resistant depression in people who suffer from childhood stress." (PMID 41011229, 2025). "Studies show that regular physical activity boosts BDNF levels and hippocampal volume—both of which are strongly associated with depression." (PMID 40964429, 2025). "Abnormal hydroxymethylation of the BDNF gene in the hippocampus, driven by neuroinflammation, is another important epigenetic factor associated with depression-like behavior." (PMID 40936908, 2025). "Anxiety and depression are closely linked to the expression of brain-derived neurotrophic factor (BDNF), with insufficient BDNF expression potentially exacerbating negative emotional states." (PMID 41030341, 2025). "BDNF is crucial for synaptic plasticity and neuronal survival, and its decreased expression has been consistently linked to depression and suicidal behavior." (PMID 40640508, 2025). "BDNF downregulation, driven by various factors, causes neurotoxic effects and is crucial for synaptic plasticity in depression." (PMID 40066336, 2025). "Chronic stress, a known risk factor for depression, can compromise this plasticity by reducing the levels of neurotrophic factors such as brain-derived neurotrophic factor (BDNF)." (PMID 39981404, 2025).
depression (continued). "The presence of the BDNF gene rs6265 polymorphism was associated with a 5.6-fold increase in the probability of depression in the cases compared to the controls." (PMID 40003622, 2025). "While low BDNF levels are linked to post-stroke depression, its role in other CVDs remains underexplored." (PMID 40491453, 2025). "Leptin increases the histone acetylation of the BDNF promoters, thus increasing the transcription of its gene, the latter process being deficient in depression." (PMID 41375608, 2025). "Exercise is known to increase BDNF levels and thus contribute to the prevention of neuronal loss and improved cognitive functioning, and, in the case of depression, it also demonstrates protective effects." (PMID 40634879, 2025). "For example, major depressive disorder is associated with impaired hippocampal plasticity, neuronal atrophy, synaptic depression, accompanied by reduced plasma BDNF levels." (PMID 40649968, 2025). "BDNF and neuroinflammation are closely associated with depression-like behavior, and BDNF expression is reduced in the hippocampus of patients with major depressive disorder." (PMID 40740995, 2025). "Second, weight loss improves insulin sensitivity and increases brain-derived neurotrophic factor, supporting neurotransmitter function and reducing depression risk." (PMID 41311799, 2025). "Dysfunction in BDNF metabolism has been implicated in many neuropsychiatric conditions, notably depression." (PMID 40005971, 2025). "Depression is associated with reduced levels of BDNF in several brain regions, including the hippocampus." (PMID 40725146, 2025). "The roles of BDNF in the CNS are vital for brain function; thus, dysregulation of BDNF function has been implicated in the cognitive impairment observed in the various mental illnesses, including depression." (PMID 40005159, 2025). "Positive emotions can also attenuate the expression of genetic vulnerability, such as BDNF Val66Met polymorphism or family history of depression." (PMID 41300812, 2025). "Exercise-induced elevation of BDNF levels has been associated with improved memory function in depression." (PMID 41477617, 2025). "A study examining several BDNF polymorphisms, including rs6265, identified the G allele as a risk factor for development of the major depressive disorder (MDD)." (PMID 41311851, 2025). "The presence of the Val66Met polymorphism of the BDNF gene in this population of subjects with MS increases the probability of presenting depression by 5.6 times." (PMID 40003622, 2025). "Given its importance, when BDNF function is disrupted, it can lead to cognitive impairment and is implicated in various mental illnesses, including depression." (PMID 40697272, 2025). "BDNF deficiency can lead to persistent dysfunction of brain regions controlling emotions and is a major factor in the pathophysiology of depression and anxiety disorders." (PMID 41155366, 2025). "Several critical BDNF signaling pathways are closely linked to depression, which can be categorized based on key proteins, such as the tyrosine kinase receptor (TrkB), the p75 neurotrophin receptor (p75NTR), and nuclear factor kappa-B (NF-κB)." (PMID 40003622, 2025). "Remarkably, reduced inflammatory markers linked to depression and increased BDNF levels point to a protective effect on mood and cognition." (PMID 41142011, 2025). "Loss of neurotrophic support by decreasing BDNF is a major mechanism of depressive disorder and has been associated with morphological changes in the hippocampus and the forebrain." (PMID 41375608, 2025). "Deficiencies or imbalances in BDNF lead to malfunction of synaptic plasticity and contribute to the development of depressive disorder." (PMID 40943672, 2025). "Since patients with depressive disorders exhibit cognitive impairments, decreased activation of the BDNF/TrkB system, which regulates neuronal function, has been considered as one of the major mechanisms underlying the pathophysiology of depressive disorders." (PMID 40005159, 2025).
depression (continued). "The presence of theMet allele interferes with normal maturation and secretion of BDNF, potentiallyinfluencing the onset, progression, and outcome of depressive disorders." (PMID 40352065, 2025). "This theory suggests that low levels of various neurotrophins, particularly BDNF, are linked to depressive disorders." (PMID 40722844, 2025). "The role of IL-6 in targeting BDNF responses for neuroregeneration and the treatment of depressive disorders is critical, particularly as exercise is associated with elevated BDNF levels." (PMID 40843259, 2025). "Feeding with HFD for 7 weeks caused obesity, anhedonia, anxiety, depression and learning and memory disorders in rats and a decrease in serum BDNF level." (PMID 40255947, 2024). "Cerebral monoamine and BDNF dysregulation are the crucial molecular mechanisms underlying the development of depression." (PMID 38279738, 2024). "This upregulation of BDNF has been associated with improved depression scores, highlighting the potential of tDCS and other NIBS methods in the treatment of depression." (PMID 38337395, 2024). "Conversely, elevated BDNF in the nucleus accumbens has been linked to increased stress vulnerability and depression-like behaviors, while reduced BDNF in this region is associated with resilience to stress." (PMID 39684808, 2024). "The results of the study showed that SNPs of eNOS, HSP70, FKBP5, miR-146a, ACE2, MAS1, SGK1, IL-4–589, IL-6–174, TNF-α–308, CRP–717, 5-HTTLPR, and BDNF genes are associated with the comorbidity of coronary heart disease and depression." (PMID 38745947, 2024). "The involvement of BDNF signaling in the effects of DMT/ayahuasca seem relevant to the association of BDNF with models of depression and anxiety disorders arising from a hyperactive immune system and chronic low-grade inflammation." (PMID 39254764, 2024). "After multivariate analysis, including admission clinical and radiological data, a low serum BDNF level at Day 1 was independently associated with an increased risk of depression in patients with cerebral infarction." (PMID 39568824, 2024). "More recently, further articles shed light on the effect of the relationship between BDNF and physical activity on humans’ cognitive function and depression; both are known to be associated with the level of AHN." (PMID 39595896, 2024). "This imbalance in E2 levels can heighten depression risk by impacting neurotransmitter production, inflammation, oxidative stress, reward circuits, and brain-derived neurotrophic factor (BDNF)." (PMID 39691784, 2024). "The pathophysiology of depression has been linked to disruptions in the serotonin–BDNF signaling pathway." (PMID 38731995, 2024). "Compared to the CG, AERE (MD = 3.36, 95% credible interval [CrI] [1.11, 5.64]), RE (MD = 3.22, 95% CrI [0.71, 5.76]), and yoga (MD = 3.04, 95% CrI [0.61, 5.43]) were all associated with significant increases in BDNF levels among patients with depression." (PMID 40226670, 2024). "Experimental models, such as intraperitoneal lipopolysaccharide (LPS) injection in rats, mimic depression-like behavior and are associated with a marked reduction in BDNF mRNA and protein expression in the hippocampus." (PMID 41221079, 2024). "It has been reported that the deregulation of BDNF is linked to the pathophysiology of depression and other mood disorders." (PMID 37953501, 2024). "In a depression model, increased miR-206-3p expression in the hippocampus was associated with a decreased hippocampal BDNF signaling cascade." (PMID 38334898, 2024). "Earlier studies have demonstrated that lower BDNF levels are linked to the pathophysiology of both depression and BD, supporting its potential as a biomarker for these conditions." (PMID 39493096, 2024). "Depression is associated with a decrease in BDNF expression, while antidepressant treatment regulates BDNF signaling and enhances its release." (PMID 38408937, 2024).
depression (continued). "Conversely, estrogen depletion or deficiency leads to decreased BDNF expression, which impairs the brain’s ability to adapt and respond to stressors, thereby increasing susceptibility to depression." (PMID 39194700, 2024). "Researchers found that the BDNF Val66Met polymorphism significantly affected the association between stress and depression in a meta-analysis of 31 trials with 21,060 participants." (PMID 38252222, 2024). "The aim of this narrative review is to first present the current knowledge in the literature regarding BDNF, its association with depression, and its relationship with traditional antidepressant treatments." (PMID 39684808, 2024). "Abnormal regulation of BDNF levels is associated with various neurological disorders, such as Parkinson’s disease, anxiety, depression, and Alzheimer’s disease." (PMID 39839860, 2024). "BDNF DNAm in blood was associated with adult stroke outcomes, including global outcome, physical disability, cognitive dysfunction, anxiety, and depression, in several candidate gene studies." (PMID 38397427, 2024). "In contrast, BDNF serves as a biological marker, providing a more objective measure of the biological changes associated with depression." (PMID 40226670, 2024). "Accordingly, low peripheral BDNF levels match with cognitive impairment in stroke patients, and BDNF epigenetic alterations correlate with memory loss and depression." (PMID 38707461, 2024). "Decreased serum BDNF is associated with a number of mental diseases, but its associations with depression and the efficacy of antidepressants have piqued the public’s curiosity." (PMID 39459643, 2024). "BDNF is implicated not only in the pathophysiology of depression but also in the therapeutic effects of antidepressants." (PMID 39650796, 2024). "According to the neurotrophic theory, a decrease in the level of BDNF in the brain can cause depression." (PMID 38408937, 2024). "A major depressive disorder is associated with reduced neurogenesis processes controlled by regulatory proteins, such as brain-derived neurotrophic factor (BDNF)." (PMID 38675471, 2024). "Since lower serum BDNF levels have been linked to a variety of neuropsychiatric disorders including depression and anxiety, further investigation of this phthalate substitute is warranted." (PMID 39330570, 2024). "Patients with alcohol-induced memory impairment are particularly susceptible to depression because depressive symptoms and cognitive impairment are closely related to damage to neuroplasticity, as evidenced by reductions in BDNF, ERK1/2, and CREB." (PMID 39126094, 2024). "As depression, neuroinflammation, oxidative stress, and decreased levels of 5-HT and BDNF represent the molecular mechanisms underlying the mutual interaction between diabetes and anxiety." (PMID 38279738, 2024). "Depression is associated with low levels of brain-derived neurotrophic factor (BDNF), which is crucial for emotional processing, memory, and learning." (PMID 39444807, 2024). "One of the most studied BDNF polymorphisms in depression and depression treatment is the Val66Met variant (rs6265), which results in a substitution of valine (Val) with methionine (Met) at codon 66 in the proBDNF protein." (PMID 39684808, 2024). "Early-life deficiency of BDNF has been linked to several mood disorders such as depression and bipolar disorder." (PMID 38879567, 2024). "Vagus Nerve Stimulation therapy for depression is closely linked to the BDNF/TrkB signaling pathway." (PMID 39734634, 2024). "Clinical studies have pointed out that altered BDNF-TrkB signaling activity is closely linked to depression." (PMID 39201490, 2024). "In our investigation, we employed Spearman correlation analyses to explore potential associations between hippocampal BDNF expression, as measured by ELISA, and parameters indicative of anxiety and depression-like behaviors." (PMID 39766310, 2024).